TIGAR (TP53 induced glycolysis regulatory phosphatase)
Diseases named in the same sentence as TIGAR in open-access papers (continued):
Sharing a sentence is not in itself a finding about the gene and the disease.
tumor (continued). "Furthermore, a heat map provided visual evidence of the reciprocal relationship between TIGAR gene expression and the diverse types of tumor-infiltrating immune cells." (PMID 39091612, 2024). "The results show that CRIF1 deficiency significantly inhibited both TIGAR and NADPH levels in BT549 cells, suggesting that TIGAR may also be implicated in inhibiting tumor cell growth and migration." (PMID 39682267, 2024). "The most notable reduction in TIGAR expression is observed in invasive tumor cells." (PMID 38247494, 2024). "However, in a neoplastic context, TIGAR helps increase the antioxidant capacity of malignant cells and favors tumor growth." (PMID 35163828, 2022). "Overexpression of both PFKFB3 and TIGAR has been observed in several tumours, where parallel increases of glycolysis and the PPP provide cells with enhanced ATP, Ribose-5-P, and TCA intermediates required for biosynthesis, together with NADPH to control ROS levels." (PMID 34299056, 2021). "Hence, cancer cells would be expected to express high levels of TIGAR and other antioxidant enzymes in favour of tumour growth." (PMID 33941245, 2021). "By decreasing ROS, TIGAR has been described as a tumor suppressor in the intestinal epithelium." (PMID 34299056, 2021). "The levels of TIGAR expression was positively correlated with tumor SUVmax of FDG uptake." (PMID 31892967, 2020). "Additionally, we have found that high TIGAR expression levels are significantly correlated with advanced tumor stages, lymph node metastasis and poor patient survival." (PMID 32206103, 2020). "Furthermore, stable TIGAR knockdown slightly decelerated HepG2 xenograft growth and enhanced the inhibitory effect of epirubicin treatment on tumor size." (PMID 30823646, 2019). "Reduced TIGAR expression could thus support tumor growth by raising levels of extracellular citrate and pyruvate." (PMID 30823646, 2019). "The role of TIGAR in tumor cell invasion and metastasis remains elusive." (PMID 29753331, 2018). "Future studies will be required to establish how TIGAR expression is regulated during stress and whether deregulation of these pathways explains the elevated expression of TIGAR seen in human tumours." (PMID 26247727, 2015). "The significant increase in TIGAR expression in the tumor cells compared with ANECs may indicate that TIGAR is involved in the development of NPC." (PMID 25621025, 2015). "In vitro, the defective growth of TIGAR-null tumor crypts could be rescued with antioxidants and nucleosides." (PMID 24383451, 2014).
tumor (continued). "Our data showed that TIGAR expression is negatively correlated with tumor SUVmax." (PMID 24363807, 2013). "Furthermore, the role of TIGAR in maintaining tumor cell survival is highlighted by the fact that some tumor types have elevated levels of TIGAR expression, and the inhibition of certain therapeutic targets is associated with a decrease of TIGAR expression." (PMID 23954639, 2013). "Notably, the TIGAR gene is a key player in tumor metabolism regulation." (PMID 39091612, 2024). "Therefore, the TIGAR is expected to become a potential target for anti-tumor therapy." (PMID 36555672, 2022). "Furthermore, TIGAR could also protect tumour cells against oxidative stress, while HK2 is crucial for energy production, preservation of mitochondrial integrity and cell survival." (PMID 32969187, 2020). "However, TIGAR overexpression can also promote the growth of tumor cells with high ROS levels." (PMID 30234009, 2018). "Administering a combination of a glutaminase inhibitor and 5FU/DDP to mice with TIGAR-overexpressing ESCC cell grafts and patient-derived tumor grafts led to significant suppression of tumor growth compared to using chemotherapy alone." (PMID 40277923, 2025). "The oncogenic relevance of TIGAR is further highlighted by in vivo evidence showing that its overexpression in MDA-MB-231, T47D, and MCF7 BC cells promotes tumor growth in a xenograft mouse model." (PMID 41345520, 2025). "TIGAR knockout in mice models was also tested, showing a significant reduction in ESCC tumor size and growth rate; furthermore, the migration and invasion were suppressed in the ESCC cell line." (PMID 40277923, 2025). "An upregulation of TIGAR in CRC tissues and benign colonic lesions was detected compared to non-tumor tissues." (PMID 40277923, 2025). "Treatment of TIGAR-overexpressing ESCC cell xenografts and patient-derived tumor xenografts in mice with a combination of glutaminase inhibitor and chemotherapeutic agents achieves significantly more efficacy than chemotherapy alone." (PMID 40277923, 2025). "Taken together our work shows that TIGAR-modulated ROS in PDAC can control cell intrinsic and extrinsic changes to impact tumor aggression." (PMID 39636862, 2024). "We investigated the expression of TIGAR in 50 normal samples and 374 HCC tumor samples derived from the TCGA dataset." (PMID 39091612, 2024). "Consistent with our previous studies showing that TIGAR loss promotes increased lung metastasis, we find that elevated TIGAR expression retards PDAC metastasis to the lung and decreases the migratory phenotype of the tumor cells in vitro." (PMID 39636862, 2024). "Of note, the deregulation of PDK1, TIGAR, and MPC1 was previously strongly correlated with tumor development." (PMID 37508533, 2023). "Treatment of TIGAR-overexpressing ESCC cell xenografts and patient-derived tumor xenografts in mice with combination of glutaminase inhibitor and chemotherapeutic agents achieves significant more efficacy than chemotherapy alone." (PMID 32206103, 2020). "Here, we demonstrate for the first time that TIGAR overexpression in ESCC cells can drive this metabolic remodeling and facilitates the tumor progression." (PMID 32206103, 2020).
tumor (continued). "High TIGAR expression and c-Myc deregulation were observed together in NOD/SCID mice engrafted with the HTLV-1+ SLB1 or MET-1 tumor lymphocytes." (PMID 31852501, 2019). "Obvious staining was shown in the cytoplasm of tumor tissue but weak in normal esophageal tissue (left), and the correlation of MUC1‐C and TIGAR was positive (right)." (PMID 30523643, 2019). "The effectiveness of GO‐203 in ESCC tumor xenografts can be related to the expression of MUC1‐C and TIGAR in human ESCC." (PMID 30523643, 2019). "Thisstudy investigated the role of TIGAR in DNA damage response (DDR) induced bygenotoxic drugs and hypoxia in tumor cells." (PMID 25928429, 2015). "Moreover, the expression of TIGAR and MUC1 transmembrane C-terminal subunit (MUC1-C) in ESCC cells is positively correlated with tumor growth, which is attenuated by targeting MUC1-C and inhibiting the AKT-mTOR-S6K1 pathway." (PMID 40002862, 2025). "Our analysis also indicates that TIGAR expression in TNBC tumor samples, though not statistically significant, is elevated compared to healthy controls." (PMID 41345520, 2025). "In intestinal adenomas, which are not metastatic, deletion of TIGAR limits the development of the tumor and improves survival." (PMID 31983610, 2020). "However, despite the delay in premalignant tumor development in the PDAC model, the capacity of these cells to metastasize is enhanced by TIGAR deletion and decreases overall survival." (PMID 31983610, 2020). "Analysis of ROS levels in these different tumor stages showed the expected correlation between high TIGAR and low ROS in PDAC lesions, with higher ROS accumulation in later stage, invasive tumors expressing lower TIGAR levels." (PMID 31983610, 2020). "Tumor tissues of mice treated with GO‐203 and CP‐2 were stained for MUC1‐C and TIGAR." (PMID 30523643, 2019). "In tumor cell lines of non-glial origin, TIGAR suppression enhanced the effect of the antineoplastic agents epirubicin, 5-fluorouracil, cis-dichlorodiamineplatinum, and etoposide, and increased the DNA damage caused by CoCl2 or epirubicin." (PMID 30823646, 2019). "Nevertheless, in mouse models, the absence of TIGAR reduces capabilities to regenerate injured intestinal epithelium and represses tumor development with ROS restriction." (PMID 30450337, 2018). "Nearly complete tumour regression was induced by TIGAR abrogation in tumour models with or without TrxR1 overexpression." (PMID 28338004, 2017). "Therefore we analyzed TIGAR expression levels in tissue samples from 79 patients with NSCLC in relation to age, gender, tumor size, histological type, histological degree and tumor staging." (PMID 24363807, 2013). "TIGAR is, without question, an important player in tumor development." (PMID 39596373, 2024). "During tumor growth, reprogrammed glucose metabolism is involved to meet the demand of glycolytic intermediates for macromolecule biosynthesis, during which the NSD2 has been reported to play a role by regulating key glucose metabolism regulators, such as TIGAR, HK2, and G6PD." (PMID 35354439, 2022).
tumor (continued). "However, this does not exclude a relevant role of TIGAR in tumor biology, as transcription and translation are known to be differentially regulated depending on cell subpopulation and environmental conditions." (PMID 30823646, 2019). "In this model the absence of TIGAR leads to a decrease in tumor formation which may indicate that suppression of ROS may be necessary during early tumorigenesis." (PMID 24756955, 2014). "Importantly, although less significant than its effect on G6PD, p52-ZER6 might also affect the expression of other glucose metabolism-related genes, such as FH, PKM2, TIGAR, LDHA, GLUT1, and HK2, thereby contributing to tumor metabolic reprogramming through multiple pathways." (PMID 36977688, 2023). "For CDKN1A, TIGAR, and PPM1D, although some genetic alterations were observed in BC cell lines and tumor samples, no significant changes in gene expression were detected across different BC subtypes." (PMID 41345520, 2025). "Using TIGAR deficient and overexpressing mouse models, we find that the impact of modulation of TIGAR and ROS in PDAC cells also has a profound effect on the normal stromal cells surrounding the tumor." (PMID 39636862, 2024).
neurological diseases (4 papers, 2019 to 2023). "TIGAR plays an important role in nervous system diseases due to its multiple physiological functions." (PMID 36437984, 2022). "Emerging evidence has proved that TIGAR plays neuroprotective effects in many neurological diseases." (PMID 31456661, 2019). "At present, the research on TIGAR in nervous system diseases is relatively rare." (PMID 36437984, 2022). "Existing studies have shown that TIGAR may be a valuable therapeutic strategy in nervous system diseases." (PMID 36437984, 2022). "At present, the research on TIGAR in nervous system diseases is relatively rare, but targeting it may be a valuable strategy." (PMID 36437984, 2022). "Future developmental clinical experiments may identify TIGAR as a potential target for the treatment of neurological diseases." (PMID 30814486, 2019). "The complex role of TIGAR in nervous system diseases and its neuroprotective effects through different mechanisms need to be further revealed, including potential agonists, inhibitors and related pathways, so as to provide references for the research of TIGAR-targeted drugs." (PMID 36437984, 2022). "Although the treatment of nervous system diseases targeting TIGAR has great application potential, it is unknown that whether promoting its overexpression would affect other tissues and organs or not, because TIGAR is expressed in many tissues and organs throughout the body." (PMID 36437984, 2022).
adenocarcinoma (2 papers, 2013 to 2021). A common cancer characterized by the presence of malignant glandular cells. "We therefore tested whether TIGAR contributes to the resistance of HPV18+ HeLa adenocarcinoma cells to chemotherapy agents that induce oxidative stress." (PMID 35291688, 2021).
hematologic malignancies (2 papers, 2017 to 2019). "Targeting MUC1-C in hematologic malignancies has been reported to inhibit TIGAR at the protein level." (PMID 28153010, 2017). "Inhibition of MUC1-C in hematological malignancies downregulates TIGAR at the protein level." (PMID 28153010, 2017).
infection (2 papers, 2021 to 2024). The state of being infected such as from the introduction of a foreign agent such as serum, vaccine, antigenic substance or organism. "The role of macrophage TIGAR in acute severe infection was examined by evaluating its response to the LPS-induced septic shock in male mice." (PMID 38773142, 2024). "In the context of infection, increased expression of TIGAR and the PPP in lymphocytes can contribute to increased capacity of these cells to maintain ROS homeostasis, allowing for the roles as secondary messengers of these radical species while at the same time preventing ROS-induced cell death." (PMID 34299056, 2021).
metabolic disease (1 paper, 2011). A congenital disorder (due to inherited enzyme abnormality) or acquired (due to failure of a metabolically important organ) disorder resulting from an abnormal metabolic process.
neurodegenerative disease (1 paper, 2022). A disorder of the central nervous system characterized by gradual and progressive loss of neural tissue and neurologic function. "TIGAR-mediated lysosomal repair also may be a potential intervention method for neurodegenerative diseases such as PD." (PMID 36437984, 2022). "This identified that TIGAR-mediated lysosome repair may be a potential intervention for neurodegenerative diseases such as PD." (PMID 36437984, 2022).
TIGAR also shares sentences with these, for which no sentence is quoted: intestinal cancer (3 papers); cardiac ischemia (2); malignant glioma (2); migraine (2); prostate carcinoma (2); acute lymphoblastic leukemia (1); adult T-cell leukemia (1); cardiomyopathy (1); cardiovascular disease (1); cervical adenocarcinoma (1); cervical squamous cell carcinoma (1); cervical tumor (1); Clear Cell Renal Cell Carcinoma (1); colitis (1); colorectal tumor (1); hypertrophy (1); invasive breast carcinoma (1); lung fibrosis (1); lymphoid tumors (1); memory (1); motor neurone disease (1); multiple system atrophy (1); Obesity (1); renal cell carcinoma (1); retinopathy (1); squamous carcinoma (1); T-cell acute lymphoblastic leukemia (1).